TEX2 (testis expressed 2)
Description:
During endoplasmic reticulum (ER) stress or when cellular ceramide levels increase, may induce contacts between the ER and medial-Golgi complex to facilitate non-vesicular transport of ceramides from the ER to the Golgi complex where they are converted to complex sphingolipids, preventing toxic ceramide accumulation.
Synonyms: KIAA1738; TMEM96; HT008
Tractability: Antibody: UniProt predicts a signal peptide or a membrane-spanning region. PROTAC: ubiquitination databases record sites on it; its protein half-life has been measured.
Gene: Protein-coding gene on chromosome 17 (64,147,227 to 64,263,291, reverse strand). Ensembl gene ENSG00000136478.
Subcellular location: Endoplasmic reticulum membrane; Nucleus membrane
Subcellular location (Human Protein Atlas): Nucleoplasm
Pathways (Reactome):
Signal Transduction: RHOA GTPase cycle
Gene Ontology:
Molecular function: lipid binding
Biological process: signal transduction; sphingolipid metabolic process
Cellular component: endoplasmic reticulum; endoplasmic reticulum membrane; membrane; nuclear membrane
Genetic constraint (gnomAD): Loss-of-function variants: 52 observed, 107.98 expected, observed/expected ratio (o/e) 0.48, 90% interval 0.38 to 0.61. The upper end of that interval is the gene's LOEUF score, 0.61, which puts it in group 2 of 6, group 1 being the genes least tolerant of losing a copy. Missense variants: 1,207 observed, 1,437.6 expected, observed/expected ratio (o/e) 0.84, 90% interval 0.8 to 0.88. Synonymous variants: 523 observed, 556.95 expected, observed/expected ratio (o/e) 0.94, 90% interval 0.87 to 1.01.
Homologues: Orthologues: chimpanzee TEX2 (99% identical), macaque TEX2 (98% identical), dog TEX2 (93% identical), guinea pig TEX2 (92% identical), mouse Tex2 (90% identical), rabbit TEX2 (89% identical), rat Tex2 (89% identical), pig TEX2 (88% identical), tropical clawed frog tex2.2 (66% identical), zebrafish tex2 (56% identical), Drosophila melanogaster CG43783 (23% identical), Caenorhabditis elegans tex-2 (23% identical).
Diseases named in the same sentence as TEX2 in open-access papers:
TEX2 is named in the same sentence as 10 diseases in open-access papers, as found by Europe PMC text mining. Sharing a sentence is not in itself a finding about the gene and the disease. The quoted sentences say what the papers report.
hepatocellular carcinoma (1 paper, 2021). A malignant tumor that arises from hepatocytes. "In contrast, circ_0004913 (gene of origin: TEX2) was found to have an opposite effect on hepatocellular cancer." (PMID 34205978, 2021). "In contrast, circ_0004913 (gene of origin: TEX2) has an opposite effect on hepatocellular cancer." (PMID 34205978, 2021).
Parkinson disease (1 paper, 2020). A progressive degenerative disorder of the central nervous system characterized by loss of dopamine producing neurons in the substantia nigra and the presence of Lewy bodies in the substantia nigra and locus coeruleus. "Protein coding genes proximal to these snoRNAs were implicated in several neurologic conditions, including Wernicke‐Korsakoff Syndrome (Tex2/SNORD104), Spinocerebellar Ataxia (Nop56/SNORD57), and Parkinson Disease (EIF4A2/SNORD2)." (PMID 33135344, 2020).
cancer (2 papers, 2019 to 2023). A tumor composed of atypical neoplastic, often pleomorphic cells that invade other tissues. "Next, the quantified tissue enrichment analysis indicated that the CD4 Tex1 and CD4 Tex2 clusters were mainly enriched in all eight types of cancer." (PMID 37313656, 2023). "Due to the frequent decreased expression of TEX2 in various cancers and lack of documented functions, we decided to further corroborate our hypothesis on the roles of YTHDF1, one of the m6A-specific mRNA binding and translation regulating proteins, in hypoxia tolerance and cancer progression." (PMID 31653849, 2019).
TEX2 also shares sentences with these, for which no sentence is quoted: breast tumors (1 paper); diabetes (1); Hypertension (1); Infertility (1); metabolic syndrome (1); Obesity (1); Spinocerebellar Ataxia (1).